CXCL12 (C-X-C motif chemokine ligand 12)
Diseases named in the same sentence as CXCL12 in open-access papers (continued):
Sharing a sentence is not in itself a finding about the gene and the disease.
tumor (continued). "Herein, using cultured cells from PTEN intact, heterozygous, and knockout cells, we show that both CXCR4 and CXCL12 expression is higher in PTEN knockout cells, thus confirming the immunohistochemical tumor expression findings." (PMID 23902739, 2013). "This has been well documented in breast cancer for the chemokine CXCL12 that, through interaction with its receptor CXCR4 in metastasizing tumor cells, directs their homing to the metastatic site." (PMID 24040160, 2013). "It was previously reported that the CXCL12 / CXCR4 axis was essential for metastatic cancer cells to disperse to organs and thereby allow tumor cells to access cellular niches that favor tumor-cell survival and growth." (PMID 24312338, 2013). "The membranous CXC chemokine receptor 4 (CXCR4) and its ligand, stromal-derived factor-1 (SDF-1), which is also known as CXCL12, are members of the chemokine family and their critical and active roles have been demonstrated in tumor growth and malignancy." (PMID 23381805, 2013). "The 5 randomly selected gene expression changes observed using the Human Tumor Metastasis RT2 Profiler PCR array (CXCR4, CXCL12, MMP2, MMP9 and MMP13) were confirmed using qPCR." (PMID 24179538, 2013). "Studies have shown that tumour cells that express CXCR4 preferentially metastasize to the bone, where its ligand, CXCL12, is abundantly expressed." (PMID 26237063, 2013). "CXCR4, together with its ligand CXCL12 (namely the CXCL12 / CXCR4 axis), is well known to be involved in many aspects of tumor progression, especially in tumor metastasis." (PMID 24312338, 2013). "In fact, CAFs elevate CXCL12 secretion, which in turn can stimulate proliferation and migration of CXCR4-expressing cancer cells in the tumor microenvironment." (PMID 22481918, 2012). "The levels of CXCL12 and CXCR4 mRNA in the primary tumor, paracancerous tissues, normal pancreas and lymph nodes surrounding the pancreas were assessed using RT-PCR." (PMID 23181100, 2012). "The anti-tumor effects of AMD3100 and AMD3465, competitive antagonists of CXCR4 activation also indicate that CXCL12 regulation of tumor growth involves activation of tumor cell CXCR4." (PMID 22427929, 2012). "Among the chemokines involved in tumor metastasis, the CXCL12 (also known as SDF-1 or stromal-derived factor)/CXCR4 axis plays a critical role in stem cell migration." (PMID 22408433, 2012). "The chemokine CXCL12, and its receptors CXCR4 and CXCR7 have been involved in tumor progression and dissemination." (PMID 22916293, 2012). "Hitherto, our results indicate that the CXCR4/CXCL12 axis is frequently expressed in EWS and affects tumor progression and patient survival by promoting cell growth." (PMID 23249693, 2012). "In order to determine the relative influence of CXCL12 and CXCR4 on other patient and tumour variables, known to affect prognosis, a multivariate analysis was performed using the Cox multivariate regression model." (PMID 22415233, 2012). "Additionally, TAMs also contribute to the angiogenic switch by releasing angiogenic factors (VEGF, FGF, and CXCL12) and to the degradation and remodeling of the matrix with metalloproteases (MMPs), suggesting an important role in neovascular formation and subsequent tumor progression." (PMID 22485156, 2012). "CXCR4 is a specific receptor for the ligand SDF-1 (stromal-derived-factor-1, also called CXCL12), and the CXCR4/CXCL12 axis has been shown to be important for tumour progression in a high number of cancer types." (PMID 22518090, 2012). "MSCs constitutively secrete the chemokine CXCL12 (SDF-1), which in turn promotes tumor progression by recruitment of endothelial progenitor cells into tumors." (PMID 22399057, 2012). "The positive rate of CXCL12 protein was 13.3% (4/30), the positive rate of CXCR4 protein was 80% (24/30) in tumor tissues." (PMID 23181100, 2012).
tumor (continued). "In a mouse model, the tumour cells with CXCR4 receptor were chemoattracted by CXCL12, migrated through the lymphatic and vascular system, and arrested in CXCL12 rich organs like the bone and lungs." (PMID 22518090, 2012). "CXCL12 is a known chemokine described in invasion and cell migration and is a ligand of CXCR4, a chemokine receptor that promotes tumor migration and invasion." (PMID 21998659, 2011). "These pDCs are recruited to the tumor microenvironment in response to several chemokines, including CCL20, stromal cell-derived factor-1/CXCL12, and Ag-5/vascular cell adhesion molecule-1 interactions." (PMID 22110524, 2011). "The role of CXCR7 further clouds the picture when attempting to understand what is more important to target while grasping CXCL12's effect on both CXCR7 and CXCR4 in the same tumor microenvironment." (PMID 22295222, 2011). "The location-based chemotaxic ability of CXCL12, combined with its affect on CXCR4-expressed cells, creates a microenvironment for tumor migration." (PMID 22295222, 2011). "Given the difference in the in vitro chemotactic and invasive behavior in response to CXCL12 stimulation of the double overexpressors, MTLn3 CXCR4-CXCR7, we proceeded to evaluate their motile behavior within the tumor microenvironment." (PMID 22152016, 2011). "The interaction of CXCL12 with CXCR4 mainly affects chemotaxis, while the binding to CXCR7 mediates proliferation in tumor cells." (PMID 20049170, 2010). "The finding that CXCR7 specifically scavenges CXCL12 suggests a critical function of the receptor in modulating the activity of the ubiquitously expressed CXCR4 in development and tumor formation." (PMID 20161793, 2010). "The MSP technique was tested with CXCL12 (island 2 and island 4) and ESR1 genes in DNA from the tumour cell lines in order to confirm the results from RT-PCR and data from the literature (ESR1)." (PMID 20109227, 2010). "Hypervascularization, tumor architecture and CXCL-12 (chemokine (C-X-C motif) ligand 12) expression are prognostic features of PNETs." (PMID 24281208, 2010). "We evaluated CXCL12 and ESR1 methylation in primary tumour samples by methylation-specific PCR (MSP)." (PMID 20109227, 2010). "Together with their CXCL12 and CCL21 ligands, CXCR4 and CCR7 were significantly highly expressed in tumor cells with lymph node (LN) metastasis." (PMID 20181250, 2010). "More importantly, their respective ligands, CXCL12 and CCL21, exhibited significant differences in expression between primary tumor and lymph node metastasis tumor (P = 0.016 and P = 0.004)." (PMID 20181250, 2010). "Although homing of macrophage to tumors is poorly understood, tumor cells are known to release macrophage chemoattractants including CCL2, CCL5, CCL7, CCL8, CXCL12, VEGF and CSF-1." (PMID 19696929, 2009). "For example, RAW 264.7 cells stimulated with tumor cell CB up-regulated several angiogenic factors (VEGF-A, HIF1α and TGF-β) and chemoattractants (CXCL12 and CXCL2)." (PMID 19696929, 2009). "Our recent results provide a novel mechanism for CXCR4-mediated tumor growth and metastasis and establish a functional link between CXCR4/CXCL12 and CCR6/CCL20 pathways in tumor development." (PMID 19340288, 2009). "The average number of nerves near the tumor tissue in the AMD3100-treated group was lowest, and the CXCL12-treated group had the highest number of nerves near the tumor tissue." (PMID 18983683, 2008). "The positive cell number of CXCL12, CXCR4, MMP-2, MMP-9 and NGF expression of tumor cells in CXCL12-treated group was the highest." (PMID 18983683, 2008). "Furthermore, estrogen can increase SDF1 (also known as CXCL12) production in cancer cells and the TME, while the SDF1/CXCR4 signaling pathway has been shown to activate ER and promote hormone-independent tumor growth." (PMID 41597220, 2026). "Additionally, DIC modulates key tumor microenvironment factors, including VEGF-A, MMP-9, IL-11, and CXCL-12." (PMID 41827705, 2026).
tumor (continued). "Tumor−derived CXCL12 and CCL5 are known to recruit suppressive myeloid and regulatory T cells, promote tumor growth, and stimulate neoangiogenesis, whereas TGF−β directly attenuates CD8+ T cell cytotoxicity and drives exhaustion in chronic inflammatory contexts." (PMID 40948762, 2025). "Once activated, CAFs secrete various bioactive molecules, including growth factors (e.g., vascular endothelial growth factor [VEGF], hepatocyte growth factor [HGF]), chemokines (e.g., CXCL12, CXCL5), and ECM proteins, thereby promoting tumor cell survival, angiogenesis, and immune evasion." (PMID 40656546, 2025). "Most importantly, preclinical studies suggest that the pharmacological inhibition of PARP not only affects DNA repair but also inhibits CXCL12/CXCR4 signalling, which influences tumour cell migration, reduces metastatic ability, and potentially increases therapeutic response." (PMID 41002447, 2025). "CTPCs are a subset of tumor cells that exit into peripheral blood as a result of the dynamic interactions between the tumor plasma cells and BM microenvironment, the most important being the CXCR4 & CXCL12 interaction." (PMID 40296907, 2025). "Furthermore, the CXCL12/CXCR4 crosstalk between macrophages and lymphocytes was significantly amplified in the tumor context, providing deeper insight into the complex interplay driving the TME dynamics." (PMID 40698080, 2025). "CXCL12 correlated with CD274 (R = 0.369) and PDCD1 (R = 0.288); CXCR4 correlated with CD274 (R = 0.579) and PDCD1 (R = 0.520), suggesting their roles in regulating immune checkpoints and tumor immune escape." (PMID 41142306, 2025). "Functionally, myCAFs promote tumor invasion by enhancing ECM deposition and remodeling matrix mechanics, whereas iCAFs modulate the immune microenvironment by secreting inflammatory factors, such as IL6 and CXCL12, to support tumor growth." (PMID 41373733, 2025). "Notably, CAF-FAP and CAF-C7 both showed upregulated chemokine signaling pathway, but showed high expression of pro-inflammatory genes (CCL2, CXCL12, GDF15, and LIFR) at tumor core and pro-fibrotic genes (TNFRSF12A, TGFBR1, TGFBR2) at FR, respectively." (PMID 39870619, 2025). "All pRMS tumor clusters use the MIF-CD74 pathway to suppress the immune response, while APP, PTN, and CXCL12 signaling are employed predominantly by the non-myogenic tumor clusters." (PMID 41373578, 2025). "Additionally, CXCL12 secretion by iCAFs creates a physical and chemotactic barrier that prevents CD8+ T cells from reaching the tumor core, aiding resistance to immune checkpoint inhibitors." (PMID 40940809, 2025). "CAFs contribute to ECM production by secreting CXCL16 and enhancing MMP expression, which increases tumor stiffness and alters ECM structure.The binding of PF4/CXCL4 and PPBP/CXCL7 to CXCL12, mediated by G protein-coupled receptors, promotes EMT and the expression of chemokines and cytokines." (PMID 40038745, 2025). "Furthermore, activated CAFs release SDF-1/CXCL12, OPN, periostin, galectin, THBS2, MFGE8, and diverse cytokines such as IL-6 and IL-32, which promote the EMT, tumor invasion, and tumor metastasis." (PMID 40352270, 2025). "Moreover, CXCL12 is highly expressed in metastatic target organs, such as the bone, liver, and lungs, where it establishes chemotactic gradients to guide CXCR4+ tumor cells to these sites." (PMID 40698080, 2025). "Furthermore, spatial transcriptomics on human PDAC tissue revealed that iCAFs using gene markers IL6 and CXCL12 and myCAFs using gene markers ACTA2 and MMP11 were spatially distributed and correlate with tumor and immune cell localizations." (PMID 41376815, 2025). "Also, a role for nectin-4 has been demonstrated in promoting tumor-induced lymphangiogenesis and lymphatic metastasis in part through modulating the CXCR4/CXCL12-LYVE-1-axis." (PMID 40507273, 2025). "CXCL12 acts through its receptor, CXCR4, which is expressed on neutrophils and tumor cells." (PMID 40486614, 2025).
tumor (continued). "The observed positive correlation between VTN and immunostimulants such as CXCL12, a chemokine critical for T cell recruitment, potentially suggests that overexpression of VTN may trigger an enhanced anti-tumor immune response in tumors." (PMID 40433359, 2025). "Experimental studies have shown that PNI in PDAC is an active process involving reciprocal tumour–nerve signalling via neurotrophic factors (e.g., NGF, GDNF, CXCL12), extracellular matrix remodelling, and Schwann cell activation, which together create a permissive niche for perineural invasion." (PMID 41227159, 2025). "Furthermore, B cells release angiogenic factors, including VEGF, CXCL12, and CXCL13, which enhance neovascularization, ensuring the tumor’s access to essential nutrients and oxygen." (PMID 40443668, 2025). "Lower levels of CXCL12 as a result of IFNγ signalling could therefore significantly re‐shape the TME of NSCLC and influence the localisation of T cells within NSCLC tumours." (PMID 39743376, 2025). "Given the importance of axon-guided migration in GBM, we included inhibitors of Ephrin receptors (ALW-II-41–27 for EphA2, NVP-BHG712 for EphB4, and Ehp-inhibitor-1), and the CXCL12/CXCR4 axis (motixafortide), known to regulate directed migration in the hypoxic tumour core in immunotherapy." (PMID 41390851, 2025). "Additionally, in the hypoxic tumor microenvironment, HIF-1α and HIF-2α stabilize and interact with co-activators to preferentially drive the expression of VEGF, CXCL12, and other genes that skew macrophages toward an immunosuppressive M2-like state." (PMID 40936918, 2025). "CXCL12 is down-regulated and epigenetically silenced in COAD and may be in-volved in early tumor suppression, offering insight into immune micro-environment modulation." (PMID 40426863, 2025). "Specifically, their pro-metastatic capacity is driven by the enrichment of the SPP1+ macrophage subset, which enhances tumor cell invasiveness and remodels the ECM through secretion of osteopontin (SPP1) and CXCL12, thereby activating pathways such as the SPP1-CD44/PTGER4 signaling axis." (PMID 40109347, 2025). "The most extensively characterized member of this family is SDF1 (CXC motif chemokine 12; CXCL12), which plays crucial roles in key physiological and pathophysiological processes such as hematopoiesis, cell migration, and tumor metastasis." (PMID 41464845, 2025). "Previous study has indicated that the down-regulation of CXCL12 in CRC cell lines and primary tumor tissues may play a regulatory role in the initiation of CRC." (PMID 40426863, 2025). "In ENKTCL, MSCs may protect tumor cells from apoptosis by secreting soluble anti-apoptotic factors (e.g., IL-6, CXCL12), altering drug metabolism in the LME and physically shielding tumor cells through the formation of protective stromal niches." (PMID 41303704, 2025). "While immunosuppressive factors such as CCL2, CXCL12, IL-4, and IL-10 sustain an immune-excluded TME, pro-inflammatory mediators like IFN-γ, TNF-α, and CXCL10 counteract these effects by promoting immune cell infiltration and tumor suppression." (PMID 40330466, 2025). "The CXCL12/CXCR4 axis plays a crucial role in tumor‐stromal cell communication and creates a favorable microenvironment for tumor growth and recruitment of CXCR4+ tumor cells to CXCL12‐rich stromal niches to initiate metastasis." (PMID 40635521, 2025). "Among them, CAFs can promote tumor proliferation, migration and drug resistance by activating PI3K/AKT, STAT3 and other pathways through secreting CXCL12, IL-6, etc., and form a pro-cancer positive feedback loop with immunosuppressive cells such as MDSC and TAM." (PMID 40860340, 2025). "Beyond secreting soluble factors, CAFs actively remodel the tumor immune microenvironment through exosome-mediated delivery of PD-L1, TGF-β, IL-6, CXCL12, and matrix metalloproteinases, directly impairing CD8+ T-cell function and promoting Treg cell and MDSC recruitment." (PMID 41439998, 2025).
tumor (continued). "Notably, CXCL12 is the only confirmed ligand for CXCR4, a key receptor broadly expressed across multiple tumor types." (PMID 40860200, 2025). "CAF release of chemokine (C-X-C motif) ligand 1 and 2 (CXCL1 and CXCL2) also increases tumor invasion, with CXCL12 further increasing macrophage recruitment, and CXCL1 increasing tumor invasion via activation of matrix-metallopeptidase 1 (MMP1), also known as interstitial collagenase." (PMID 40872475, 2025). "As such, the blockade of CXCR4 in combination with other radiosensitising approaches can be ideal to enhance treatment response and reduce relapse in TNBC by targeting tumour cells and reconstructing the protective microenvironment mediated by CXCR4/CXCL12 signalling." (PMID 41002447, 2025). "MMPs contribute to the sprouting of vascular endothelial cells by degrading the vascular basement membrane and extracellular matrix in the early stages of tumor angiogenesis, and CXCR4/CXCL12 signaling pathway mediates cell migration signals and metastasis processes." (PMID 39965034, 2025). "CXCL12 plays a nuclear role in tumor-intrinsic EMT, invasion, survivability, and metastatic seeding mediated by tumor intrinsic CXCR4 signaling (through PI3K/AKT, MAPK/ERK, JAK/STAT) as well as CXCL12 chemotaxis induced by microenvironmental CXCL12 in stromal and endothelial cells." (PMID 41383468, 2025). "This suggests that the role of CXCL12 in OSCC is complex and multifaceted, which may be related to the role of CXCL12 in different tumor stages and different microenvironments." (PMID 41445742, 2025). "Furthermore, hypoxia increases the mRNA and protein expression of anti-tumor immunity factors including TGF-β, IL-10, VEGF, CXCL12, PD-L1, FasL, and CD39 on CAFs." (PMID 40963621, 2025). "The CXCL12/CXCR4 axis recruits monocytes, induces their differentiation into M2 macrophages, and promotes OSCC cell transformation into cancer stem cell (CSC)-like phenotypes, thereby accelerating tumor proliferation." (PMID 41445742, 2025). "For example, CD3+ T cells were also observed in some CXCL12-negative stroma, and it was technically challenging to directly evaluate the CXCL12-mediated effects of CAFs and tumor cells in vitro." (PMID 40849508, 2025). "Tumor cell homing, metastasis, and maintenance of cancer stem cells are all significantly regulated by CXCR4, which acts in part through interaction with the CXCL12 axis and co-opted in the signals from TGF β to increase invasiveness." (PMID 41348904, 2025). "Furthermore, CXCL12 participates in chemotherapy-induced EMT and regulates interactions between tumor cells and CAFs." (PMID 41445742, 2025). "Additionally, the SVZ was found to drive GBM invasion through the secretion of various chemical factors, such as pleiotrophin (PTN) complexes and C-X-C motif chemokine 12 (CXCL12), inducing angiogenesis and providing nutrients for tumor growth." (PMID 39935607, 2025). "The findings of the present study indicate that CAFs are involved in T cell recruitment through the CXCL12/CXCR4 axis, which may influence the efficacy of tumor immunotherapy." (PMID 40849508, 2025). "Inhibition of this pathway has been demonstrated to reduce metastasis in breast cancer, likely through the disruption of CXCL12/CXCR4 signaling, which impairs chemotactic and invasive responses of tumor cells and limits their spread to regional lymph nodes and lungs." (PMID 40943634, 2025). "It is widely acknowledged that chemokines secreted by tumor cells such as CCL2, CCL5, CCL7, CCL20, CXCL2, CXCL8 and CXCL12 significantly contribute to the recruitment of monocytes and macrophages during neoplastic transformation, among which CCL2 plays a key role in TAM recruitment." (PMID 40380196, 2025). "Notably, NF-κB activation also upregulates CXCL12 and CCR9 expression, creating a positive feedback loop that sustains tumor-promoting inflammation and chemokine signaling." (PMID 40607416, 2025).